MYD88 (MYD88 innate immune signal transduction adaptor)
Diseases named in the same sentence as MYD88 in open-access papers (continued):
Sharing a sentence is not in itself a finding about the gene and the disease.
food allergy (11 papers, 2018 to 2023). Gastrointestinal disturbances, skin eruptions, or shock due to allergic reactions to allergens in food. "The underlying mechanism of Clostridiales‐mediated protection from food allergy was found to be the expansion of intestinal Treg cells via MyD88‐dependend signals working directly on the Treg cells." (PMID 35152475, 2022). "Certain species of bacteria, including some in the genus Clostridia, have been shown to confer protection against development of food allergies by contributing to the development of peripherally expanded protective RORγ+ T cells in a MYD88-dependent manner." (PMID 33362785, 2020). "Bacteriotherapy with Clostridiales species, impacted by dysbiosis in human infants with food allergy, suppressed food allergy in mice via MyD88/ROR-γt+ Treg cell pathway, indicating that microbiota critically regulate food allergy." (PMID 31507589, 2019). "In addition, it has been recently reported that certain bacterial species such as Clostridiales suppressed food allergy in mice via induction of ROR-γt+ regulatory T cells in a MyD88-dependent manner." (PMID 32117293, 2020). "Experiments have recently been reported in which inoculation of Clostridiales species, either as a consortium or as monotherapy with Subdoligranulum variabile, or a Bacteroidales consortium could reduce development of food allergy in OVA sensitized mice by acting through MyD88 and RORγt." (PMID 35769569, 2022). "Subdoligranulum, a member of the Ruminococcaceae family, can activate the neonatal Treg cells’ MyD88/ROR-γt pathway, thus effectively preventing food allergies." (PMID 37560527, 2023). "MyD88 is a downstream molecule involved in TLR signal transduction and inhibits food allergy through the MyD88/RORt+ pathway of regulatory T cells." (PMID 36141041, 2022).
Hepatitis (11 papers, 2017 to 2025). Inflammation of the liver. "The results showed that MPs and Cd induced intestinal damage and liver inflammation in broilers by interfering with the TLR4/MyD88/NF-κB pathway and intestinal flora homeostasis." (PMID 40278565, 2025). "A previous study also demonstrated that concanavalin A-induced hepatitis requires MyD88-dependent signaling." (PMID 29144391, 2017). "Oppositely, it was found that FGP and SGP intervention significantly inhibited the expression levels of TLR4, MyD88, p‐P65/P65, p‐IκBα/IκBα, and p‐NF‐κB/NF‐κB, suggesting that FGP and SGP attenuated CTX‐induced liver inflammation." (PMID 41256228, 2025). "For example, it has been reported that the TLR4/NF-κB/MyD88 signaling pathway can induce the transcription and expression of a variety of pro-inflammatory chemokines, such as IFN-γ and TNF-α, related to liver inflammation." (PMID 38931473, 2024). "In the present work, the antinflammatory capability of Baishouwu extract mainly resulted in decreased levels of MyD88, TRAF6, NF-κB, IL-6 and TNF-α via the reduction of TLR4 expression in hepatitis, cirrhosis, and hepatocarcinoma stages of the HCC models induced by DEN." (PMID 31068809, 2019). "Furthermore, TLR4 overexpression induced by DEN was decreased by Baishouwu extract, leading to the markedly down-regulated levels of MyD88, TRAF6, NF-κB p65, TGF-β1 and α-SMA in hepatitis, cirrhosis, and hepatocarcinoma." (PMID 31068809, 2019). "The reduced expression levels of TLR2, TLR4 and TLR9 mRNAs or proteins can enhance protection against T cell-mediated hepatitis in mice, and the reduced expressions of TLR4, MyD88 and NF-κB may mediate the protective effects against LPS through reducing the level of pro-inflammatory cytokines." (PMID 30909396, 2019).
pneumococcal infection (11 papers, 2013 to 2025). Infections with bacteria of the species streptococcus pneumoniae. "We further found that MyD88-/- PMNs produced less MitROS in response to pneumococcal infection suggesting that released bacterial products acting as TLR ligands are sufficient for inducing MitROS production in PMNs." (PMID 36374941, 2022). "In particular, deficiencies in IL-1 signaling, including in IRAK4, Myd88 and NEMO, are associated with susceptibility to severe and recurrent pneumococcal infections during childhood." (PMID 30379943, 2018). "In human patients with mutations in MyD88 (encoding the intracellular adapter that transduces TLR signals), susceptibility to pneumococcal infections is increased." (PMID 23527286, 2013). "MyD88 synergizes with the cyclic GMP-AMP synthase-stimulator of interferon genes (cGAS-STING)pathway in Ly6Chi monocytes to enhance IFN-γ production during Streptococcus pneumoniae infection." (PMID 41293166, 2025). "Studies have shown that MyD88-deficient mice exhibit significantly higher viral loads in the lungs following SARS-CoV infection, and display increased susceptibility and mortality during Streptococcus pneumoniae infection." (PMID 41293166, 2025). "In summary, the activation of the STING pathway in monocyte/monocyte-derived cells can synergize with the MyD88 pathway to drive IFNγ production during pneumococcal infection that may influence the development of adaptive immunity." (PMID 34512626, 2021). "Upon intranasal pneumococcal infection, Tlr7/9/13–/– mice (but not the respective single-KO strains) displayed a Myd88–/–-like phenotype and rapidly succumbed to infection." (PMID 38358825, 2024). "The indistinguishable disease phenotypes of Tlr2/13–/– and Tlr2/4/13–/– mice, along with their similarity to the Myd88–/– disease phenotype, suggest that TLR2 and -13 are the primary drivers of innate immune activation during pneumococcal infection of the murine CNS." (PMID 38358825, 2024). "In each experiment, we included for comparison mice lacking MyD88 or TLR2, each of which has been previously studied in similar models of pneumococcal infection." (PMID 32209688, 2020).
dermatitis (10 papers, 2014 to 2025). An inflammatory process affecting the skin. "Finally, we observed complete protection from dermatitis when ΔKerOTULIN mice were crossed onto a MyD88-deficient genetic background, suggesting that microbial components could be involved in driving dermatitis in OTULIN-deficient skin." (PMID 34625556, 2021). "Skin inflammation was dependent on IL-1R and IL-36R signals as well as their signaling adaptor MyD88." (PMID 34054828, 2021). "Hh also reduced expression of other genes for inflammatory signaling pathways implicated in skin inflammation including TNFR (Tnfrsf25), JAK-STAT (Jak1), and NF-κB (Trl4, Myd88, Cd69, Cd48, Irf1)." (PMID 31264977, 2019). "IL-36R/MyD88 signaling induces T cell production of IL-17 to drive skin inflammation." (PMID 35456097, 2022). "Therefore, we identified a critical role of IL-33 signaling via ST2 and uncovered the pivotal function of MyD88 in DCs in MC903-induced AD-like skin inflammation." (PMID 28383552, 2017). "Additionally, specific deletion of MyD88 in DCs prevented the development of dermatitis with decrease expression of the proinflammatory cytokines IL-6 and IL-12, and different B cell-stimulating cytokines, including IL-10 with hampered B cell proliferation in MRL.Faslpr mice." (PMID 31546763, 2019). "For example, during Staphylococcus aureus exposure, IL-36α secretion from keratinocytes induces skin inflammation characterized by the infiltration of γδT cells, CD4+ T cells, and neutrophils via MyD88 signaling." (PMID 40563457, 2025). "Clinical signs of skin inflammation and inflammatory cell infiltration were drastically reduced in the absence of MyD88." (PMID 28383552, 2017). "However, deleting MyD88 in dendritic cells (DCs) did not affect nephritis, despite the importance of DCs in renal inflammation, whereas MyD88 deletion in DCs did reduce dermatitis." (PMID 40710333, 2025).
Hypertension (10 papers, 2019 to 2026). The presence of chronic increased pressure in the systemic arterial system. "MyD88 deficiency attenuated AngII-induced hypertension and endothelial dysfunction in conductance and resistance vessels, surpassing the effect of single TLR deficiencies." (PMID 41993090, 2026). "In this study, we aimed to determine the role of MyD88 and the underlying mechanisms in hypertension." (PMID 40682481, 2025). "Up to date, a growing body of evidence has associated the TLR4/MyD88/NF-κB pathway within the brain with pathological hypertension, whereas RAS and sympathetic nervous system (SNS) are involved in regulating blood pressure." (PMID 33324685, 2020). "Our previous results confirmed that the TLR4/MyD88/NF-κB signaling pathway in the PVN regulates the downstream transcription factors of cytokines in the context of hypertension." (PMID 35204171, 2022). "Current research on the role of the TLR4/MyD88/NF‐kB axis in the PVN in cardiovascular disease has mainly focused on hypertension." (PMID 35393774, 2022). "In this study, we demonstrated that aerobic ExT is beneficial for hypertension treatment through the modulation of TLR4/MyD88/NF-κB signaling in the PVN." (PMID 31708733, 2019). "Additionally, we performed biodata analyses from a population-based cohort study and human protein network interactome analyses to understand the role of MyD88 in hypertension." (PMID 41993090, 2026). "Previous studies reported the opposite roles of MyD88 in hypertension." (PMID 40682481, 2025). "Collectively, this study reveals that ExT could attenuate RSNA and blood pressure, and inhibit TLR4/MyD88/NF-κB signaling in the PVN of 2K1C hypertension." (PMID 31708733, 2019). "Silencing macrophage-specific expression of MyD88, the molecular adaptor protein downstream of IL-1R1 stimulation, also disrupted the progression of PH in mice, leading to the speculation that the IL-1R1/MyD88 interaction is vital for facilitating signaling events that lead to hypertension." (PMID 34445357, 2021). "In summary, abundant evidence shows that 2K1C renovascular hypertensive rats had significant upregulation of TLR4/MyD88/NF-κB signaling transduction within the PVN and contributes to the pathogenesis of hypertension." (PMID 31708733, 2019). "All these data indicated that cardiomyocyte deletion of MyD88 did not affect the hypertension and serum Ang II level." (PMID 40682481, 2025). "Furthermore, NKA α2 shRNA restored the balance of pro- and anti- inflammatory cytokines as well as decreased the TLR4, MyD88, and NF-κB p65 expression in the PVN during the development of hypertension." (PMID 35204171, 2022). "BBR (1.25, 2.5, and 5 μmol/L) could inhibit the apoptosis of aortic endothelial cells isolated from SHR, decrease the expression of TLR4, MyD88, NF-κB, IL-6 and TNF-α, and have a certain protective effect on hypertension-induced vascular endothelial injury." (PMID 33815112, 2021). "Hence, NKAα2 regulates the TLR4/MyD88/NF-κB signaling pathway and induces the PVN neuroinflammatory responses in the PVN, thus elevating blood pressure and sympathetic activity in the context of salt-induced hypertension." (PMID 35204171, 2022).
nephritis (10 papers, 2015 to 2025). Inflammation of renal tissue. "Extracellular HMGB1 has been reported to increase macrophage inflammation and is highly correlated with histopathological features of renal injury in active nephritis via the TLR4/MyD88/NF-κB/p65 signaling pathway in LN." (PMID 37872565, 2023). "Here, CM inhibited the expression of the TLR4/MyD88/NF-κB signaling pathway, which was in consistence with a previous report showing that CM fruit body extract relieved nephritis by inhibiting the TLR4/NF-κB signaling pathway." (PMID 35369439, 2022). "This led us to concern that the inflammatory injury of nephritis in LN may be closely related to the activation of TLR4/MYD88 pathway mediated by NETs." (PMID 41208960, 2025). "Concurrently, it inhibited the mRNA expression of renal inflammatory cytokines via the inhibition of NLRP3/Caspase-1 and TLR4/MyD88/NF-κB signaling pathways, thereby alleviating the HUA-induced kidney inflammation." (PMID 41300001, 2025). "The results of this study also found that lycopene can alleviate high-fat diet-induced nephritis in mice, mainly by regulating the expression of the TLR4/MyD88 pathway and its downstream inflammatory factors." (PMID 36230117, 2022). "In order to further verify the effect of lycopene on the TLR4 pathway in nephritis mice from the protein level, we investigated the protein levels of TLR4, TRIF, MyD88, and NF-κB." (PMID 36230117, 2022).
peritonitis (10 papers, 2011 to 2025). Inflammation of the peritoneum (tissue that lines the abdominal wall and covers most of the organs in the abdomen). "Employing a peritonitis mouse model, we found that the deficiency of the tlr2/tlr4, myd88 and trif results in decreased neutrophil influx to peritoneal cavities of mice, indicative that in addition to MyD88, TRIF contributes to neutrophilia triggered by TLR4 engagement by Natterin." (PMID 35408954, 2022). "Additionally, A. muciniphila has been shown to mitigate peritonitis and promote colonic wound healing via a MyD88-dependent pathway of the innate immunity." (PMID 41472021, 2025). "In a first experiment, we determined whether the intestinal-epithelial-cell-specific inactivation of MyD88 itself had any effect on body weight, survival, and peritonitis severity." (PMID 36078075, 2022). "By using MyD88 knockout and TLR2 knockout mice, it was previously shown that MyD88 contributes to the effective clearance of E. faecium during peritonitis at least in part via TLR2/MyD88 signaling pathway and by facilitating neutrophil recruitment to the site of infection in vivo." (PMID 26317438, 2015). "We speculate that downregulation of Cox-2 through TLR-2/TLR-4 (via MyD88) in the lungs of Lactobacillus rhamnosus GG or Bifidobacterium longum treated mice may play a protective role in attenuating inflammation induced lung injury following systemic sepsis and peritonitis." (PMID 24830455, 2014). "This peritonitis response occurred independent of MyD88 signaling, though at a lower level." (PMID 21386979, 2011).
steatosis (10 papers, 2010 to 2025). Increased lipid within the cytoplasm of cells. "Alcohol feeding with the Lieber-DeCarli diet resulted in significant steatosis and liver damage in MyD88-deficient mice compared to mice on pair-fed diet, and the extent of alcohol-induced changes was comparable in alcohol-fed MyD88-deficient and wild-type mice." (PMID 20827314, 2010). "Zhang study revealed increased MyD88 mRNA expression in HBV-transgenic mice having non-alcoholic fatty liver disease as well as in HepG2.2.15 cells treated with stearic acid to induce steatosis." (PMID 27135246, 2016). "HMGB1 exacerbates inflammation through activation of TLR4/MyD88 signaling and RAGE receptors in hepatocytes, resulting in pyroptosis, liver damage, steatosis, and impaired liver function." (PMID 39000266, 2024). "Together, these data support the anti-steatosis effect of PM2.5-triggered hepatic autophagy and the requirement of MyD88 for PM2.5-triggered hepatic autophagy." (PMID 29176715, 2017). "Chimeric mice with Kupffer cells that do not express MYD88/TRIF or TLR2 were protected from E. faecalis -exacerbated alcoholic liver injury, steatosis, inflammation, and fibrosis, compared with chimeric mice with WT Kupffer cells." (PMID 29038503, 2017). "Thus, the adaptor protein MyD88 is not essential for TLR4-mediated alcoholic liver injury and steatosis." (PMID 28852648, 2017).
abscess (9 papers, 2008 to 2025). An inflammatory process characterized by the accumulation of pus within a newly formed tissue cavity which is the result of a bacterial, fungal, or parasitic infection or the presence of a foreign body. "In contrast to WT mice, MyD88 KO mice showed foci of liver necrosis and the formation of small abscesses." (PMID 18946505, 2008). "To determine which downstream pathway regulates abscess susceptibility, we infected B6J females lacking Myd88 or TRIF." (PMID 38096412, 2023). "Interestingly, we have shown that IL-1β/MyD88 actions in neutrophils are necessary for S. aureus abscess formation." (PMID 30102746, 2018). "Myd88-/- mice displayed small numbers of neutrophils in the panniculus, but no mice (0/5) displayed a well-defined abscess." (PMID 28704551, 2017). "Kidneys of Tlr4−/− and Myd88−/− mice infected with CFT073 or the ΔTcpC mutant were normal in size, color and texture and had no abscesses." (PMID 20886104, 2010).
Anxiety (9 papers, 2015 to 2026). Intense feelings of nervousness, tension, or panic often arise in response to interpersonal stresses. "In contrast to our results from TLR-2 KO mice, it has been reported that the Myd88 deficiency in C57BL/6 mice showed more anxiety, better motor coordination, and improved spatial learning than WT mice." (PMID 25687169, 2015). "Treatment with dex significantly reduced the expression of TLR4, MyD88, and NFκBp65 in HH-exposed rats and alleviated neuroinflammatory responses and anxiety-like behaviors." (PMID 41222826, 2025). "Myeloid differentiation primary response protein 88 (MyD88) knockout in mice resulted in decreased motor activity and elevated levels of anxiety-like behavior." (PMID 36437953, 2022). "Furthermore, LPS-RS did not significantly alter behavior, suggesting that the MyD88 pathway may not be involved in anxiety-like and repetitive behaviors generated by gut-derived endotoxin." (PMID 29351816, 2018).
cardiomyopathy (9 papers, 2016 to 2024). A disease of the heart muscle or myocardium proper. "NLRP3 inflammasome and Myd-88 activation have been implicated in several diseases, including cancer and cardiomyopathies." (PMID 38818214, 2024). "It would be important to determine the exact contribution of TRIF‐driven IFNs, although our data showed that inhibition of MyD88 arm of the TLR pathway with Sch B, or MyD88 gene knockout, almost completely prevented cardiomyopathy." (PMID 36180407, 2022).
chronic obstructive pulmonary disease (9 papers, 2021 to 2025). A chronic and progressive lung disorder characterized by the loss of elasticity of the bronchial tree and the air sacs, destruction of the air sacs wall, thickening of the bronchial wall, and mucous accumulation in the bronchial tree. "The critical role of MyD88 in pro-inflammatory signaling associated with severe inflammation especially in chronic lung diseases such as chronic obstructive pulmonary disease (COPD) is summarized in a recent review." (PMID 33834387, 2021). "Clinical trials using MyD88-targeted therapy for chronic obstructive pulmonary diseases have shown promising results." (PMID 39247623, 2024). "HMGB1 activates Aspergillus fumigatus in alveolar macrophages in chronic obstructive pulmonary disease through the MyD88/NF-κB and syk/PI3K signal transduction pathways, leading to inflammation." (PMID 33979394, 2021). "Previous reports have shown that in a chronic obstructive pulmonary disease (COPD) inflammatory model, SH attenuated inflammation by reducing the mRNA levels of TLR4, MyD88, and NF-κ B p65 and the protein expression of TLR4 and p65." (PMID 33716736, 2021).